CD34 (CD34 molecule)
Diseases named in the same sentence as CD34 in open-access papers (continued):
Sharing a sentence is not in itself a finding about the gene and the disease.
chronic myeloid leukemia (74 papers, 2002 to 2025). "Tenovin‐6 (a small‐molecule inhibitor of SIRT1 and SIRT2) treatment yielded a significant loss of imatinib‐resistant chronic myeloid leukemia (CML) CD34+ stem cells in vivo." (PMID 28994177, 2017). "Anisomycin can inhibit the proliferation of chronic myeloid leukemia (CML) CD34 stem cells and induce apoptosis, and the combination of imatinib or dasatinib can significantly improve their efficacy." (PMID 37325053, 2023). "Attenuation of Stat5a is sufficient to enhance basal oxidative stress in normal CD34+ and chronic myeloid leukemia cells." (PMID 35812340, 2022). "The downregulation of miR-10a in chronic myeloid leukemia CD34+ cells increases USF2-mediated cell growth and increases the cisplatin resistance of lung adenocarcinoma circulating tumor cells via targeting PIK3CA in the PI3K/Akt pathway." (PMID 34062897, 2021). "Another set of 153 genes were found to be enriched in CD34+ cells isolated from the BM of patients with chronic myeloid leukemia (CML) compared to those from normal donors (overlap = 153/1,399, P = 2.400e-25)." (PMID 33014825, 2020). "In studies using CD34 + cells isolated from chronic myeloid leukemia patient bone marrow, sub-toxic levels of arsenic trioxide enhanced or primed erythroid colony forming activity." (PMID 33214633, 2020). "FGFR3, an important member of the FGFR family, is highly expressed in HSCs, and increased in LSCs (CD34+BCR-ABL+) from chronic myeloid leukemia (CML)." (PMID 33584313, 2020). "Previous studies showed that hsa-miR-326 inhibited SMO expression in glioma cancer and CD34(+) chronic myeloid leukemia cells and acted as a tumor suppressor miRNA by inhibiting the PI3 kinase pathway in glioblastomas." (PMID 30777071, 2019). "In particular, it was found that knockdown of ATG4B by siRNA suppresses growth and survival of CD34+ chronic myelogenous leukemia (CML) progenitor cells and sensitises them to treatment with imatinib mesylate." (PMID 31878323, 2019). "This was verified in total blood where the huge cellular volume of erythrocytes constituted a large reservoir of dasatinib able to induce apoptosis in naïve BCR-ABL1 cell lines and primitive chronic myeloid leukemia (CML) CD34+ cells." (PMID 31723769, 2018). "To identify biomarkers predicting deep molecular response we performed transcriptional profiling on CD34+ progenitor cells from newly diagnosed chronic phase chronic myeloid leukemia patients treated with nilotinib on a prospective clinical trial." (PMID 29707154, 2018). "This reinforces the central role of STAT5 in the maintenance of chronic myeloid leukemia, in accordance with the known effects of this transcription factor on cell cycle, apoptosis, production of ROS and the sensitivity of CD34+ cells to TKI." (PMID 29100302, 2017). "At present, our study is limited by using one myeloblastic cell line, K562, derived from chronic myeloid leukemia, and total samples of CD34+ stem cells and progenitors isolated from bone marrow." (PMID 28301528, 2017). "We tested the detection capability of the SC-QDP for identifying rare kinase inhibitor insensitive cells by assaying single CD34+ cells obtained from patients with chronic myelogenous leukemia (CML)." (PMID 27320899, 2016). "We demonstrate that the SC-QDP quantitates phosphoresponse heterogeneity in human acute myeloid leukemia MOLM14 cells to kinase inhibitor drugs (KIs) and identifies KI-insensitive CD34+ cells in patients diagnosed with chronic myeloid leukemia." (PMID 27320899, 2016). "Our previous study in chronic myeloid leukemia (CML) found that Tim‐3 was highly expressed in a subset of CD34+CD38+CD123high progenitors and could be a simple and less addressed surface marker of CML LSC." (PMID 36545697, 2023).
chronic myeloid leukemia (continued). "Additionally, p62 expression and autophagy were induced by resveratrol in CD34+ precursor cells in chronic myelogenous leukemia patients, and inhibition of autophagy protected CD34+ chronic myelogenous leukemia cells from resveratrol-mediated cell death." (PMID 36430164, 2022). "We recently showed that the DNA methylation alterations of CD34+CD15− chronic myeloid leukaemia (CML) cells affect alternative splicing genes, suggesting that spliceosome actors might be altered in chronic-phase (CP)-CML." (PMID 36230624, 2022). "Moreover, hTERT has been demonstrated to be downregulated in the CD34+ haematopoietic stem cells of patients with chronic myeloid leukemia." (PMID 31921617, 2019). "In agreement with our observations, analysis of one publicly available microarray experiment dataset on 4-HPR-treated and untreated CD34+ cells from four chronic myeloid leukemia patients (GEO Accession: GSE17480) showed that the retinoid induced a six-fold increase in AF1q mRNA expression (P<0.01)." (PMID 22761939, 2012). "This study aimed to assess the impact of the CD34+/CD38- stem cells (SCs) burden in chronic myeloid leukemia (CML) on treatment response and patients’ outcomes." (PMID 34711000, 2021). "In chronic myeloid leukemia (CML) patients, high BCRP expression was noticed in early CML cell populations and CD34+ cells." (PMID 38413011, 2024). "Due to the expression being in the fraction CD34+/CD38− LSCs, with a phenotype very similar to that of chronic myeloid leukemia (CML), the authors further confirmed the relationship between the two entities." (PMID 35205639, 2022). "Chronic myeloid leukemia (CML) are initiated and sustained by self-renewing malignant CD34+ stem cells." (PMID 35444236, 2022). "In the blast phase (blast crisis) of chronic myeloid leukemia and in acute lymphoblastic leukemia, NSG‐engrafting stem cells are also found in both, the CD34+/CD38− and CD34+/CD38+ subfraction of leukemic cells." (PMID 32657052, 2020). "We analyzed CD34+ bone marrow cells from subjects with AML (16 total), chronic myeloid leukemia (5 total) or normal control individuals (4 total)." (PMID 25531430, 2014). "Replacing CD34+ progenitors of chronic myeloid leukemia in growing conditions is deleterious if autophagy is blocked by the inhibition of the initiating step involving the PI3-kinase class III, Vps34, while sparing normal CD34+ progenitors." (PMID 35053612, 2022). "The upregulated miR-326 was revealed to decrease SMO expression, resulting in an elevated rate of apoptosis in chronic myeloid leukemia (CML) cells, which could be beneficial in eradicating CD34+ CML stem cells." (PMID 34959397, 2021). "Based on our previous work in chronic myeloid leukaemia, we first analysed miR-17∼92 expression in ALL and observed a significantly lower expression in ALL as compared to normal CD34+ cells with further reduction in BCR-ABL-positive as compared to -negative ALL cells." (PMID 24280866, 2014). "Venurini and colleagues found that the miR-17-92 cluster was up-regulated in CD34+ cells from healthy subjects and those with early-chronic phase chronic myelogenous leukemia, but was not up-regulated in CD34+ cells from subjects with CML blast crisis." (PMID 18647411, 2008). "Similarly, in CD34+ leukemic stem cells (LSCs) derived from patients with chronic myeloid leukemia, metabolic analysis revealed increased levels of OXPHOS compared to CD34− cells, while inhibition of this process resulted in their selective eradication in vitro." (PMID 36497394, 2022). "PN has been reported to trigger a robust apoptosis in primitive CD34+ cell population from acute myelogenous leukemia (AML) specimens while sparing normal hematopoietic cells and can induce cell death in primitive chronic myelogenous leukemia (CML) cells through reactive oxygen species." (PMID 32823992, 2020).
chronic myeloid leukemia (continued). "This was demonstrated by Sconocchia and coworkers who found an MICA/B overexpression on chronic myelogenous leukemia CD34 cells but not on normal CD34 cells and showed that this upregulation correlated with the ability of soluble MICA (sMICA)/B to bind to the NKG2D receptor." (PMID 28396673, 2017). "We have now demonstrated that pimozide, an FDA-approved anti-psychotic drug that is used in the treatment of a wide range of diseases and could be potentially used to treat chronic myeloid leukemia, in which it specifically targets cancer cells, without affecting CD34+ hematopoietic stem cells." (PMID 28459842, 2017). "Id genes are frequently overexpressed in advanced stage chronic myeloid leukemia (CML), AML and MDS patient samples while low or no levels of ID1 were detected in normal CD34+ HSPCs." (PMID 35990659, 2022).
lymphoma (74 papers, 2006 to 2025). A malignant (clonal) proliferation of B- lymphocytes or T- lymphocytes which involves the lymph nodes, bone marrow and/or extranodal sites. "Following this, we detected a tenfold increased expression of the alternative anti-apoptotic MCL1 in healthy CD34 + cells compared to lymphoma cell lines, protecting the progenitor cells from long-lasting abolishment of BCL2 by VEN." (PMID 39531065, 2025). "Only baseline CD34+ cell counts on Day +4 (P-value = 0.002) and lymphoma diagnosis (plasma cell disorders versus lymphoma - P-value = 0.041) were significantly associated with apheresis success." (PMID 39306579, 2025). "A recent study reveals that CD34+CD19+ cells are indicated as candidate lymphoma stem cells (LSC) and follicular lymphoma patients have a higher percentage of these cells in BM." (PMID 41296384, 2025). "In fact, CD34 + cells have similar levels of BCL2 to lymphoma cell lines due to their immaturity but were not as dramatically affected by VEN." (PMID 39531065, 2025). "The total number of CD34+ cells obtained in PMs with lymphoma was lower than that achieved with our protocol (median: 4.3 vs. 12.9×106/kg)." (PMID 39091501, 2024). "Here we retrospectively studied the efficacy and safety of CD34+ PBSC mobilization using EA followed by G-CSF in 98 r/r lymphoma patients, including 39 predicted poor mobilizers (PMs)." (PMID 39091501, 2024). "Remarkably, a single apheresis session was sufficient for collecting an adequate number of CD34+ cells for ASCT in 89.7% (n=35/39) of lymphoma patients, a significantly higher rate compared to reported outcomes with plerixafor (56.5%)." (PMID 39091501, 2024). "Our findings indicate that EA plus G-CSF is an effective and tolerable CD34+ stem cell mobilization strategy for patients with r/r lymphoma, including those predicted to be PMs." (PMID 39091501, 2024). "We utilized CD34+ hematopoietic cells from the bone marrow of the lymphoma patients, since the bone marrow of aplastic anemia patients is known to contain very few CD34+ hematopoietic cells." (PMID 39337644, 2024). "Among the 26 lymphoma patients, 21(80.8%) collected adequate amount of CD34+ cells, while only 12(46.2%) achieved optimal mobilization." (PMID 39091501, 2024). "The high quantity of CD34+ cells collected through our EA protocol not only meets the criteria for aggressive lymphoma patients undergoing ASCT for consolidation treatment but also allows for partial cryopreservation of cells." (PMID 39091501, 2024). "The overall success rate defined as ≥2 × 106/kg CD34+ cells in patients with lymphoma was 87% in the Plerixafor Group compared to 100% in the G-CSF Group (p = 0.003)." (PMID 36765566, 2023). "The median CD34+ cell number re-transfused per transplant in myeloma patients was similar in both groups, whereas in lymphoma patients a significantly lower CD34+ cell number was re-transfused in the Plerixafor Group (p = 0.03)." (PMID 36765566, 2023). "The target CD34 cell yields were ≥2.0 × 106 CD34+ cells/kg in lymphoma and ≥4.0 × 106 CD34+ cells/kg in myeloma patients to enable putative second transplants in the latter." (PMID 36765566, 2023). "In the case of CD34+ lymphoma, it can be presumed to be a precursor-derived or remaining aberrancy in the differentiation stage of tumor cells or leukemic involvement in high-grade lymphoma." (PMID 37908841, 2023). "Overall, Plerixafor led to a 7-fold increase in CD34+ cell numbers in peripheral blood in the entire cohort (myeloma and lymphoma patients) with a significantly greater increase in myeloma than in lymphoma patients (8-fold vs. 4-fold, p < 0.001)." (PMID 36765566, 2023). "MM patients have shown a more favorable CD34 cell count than Lymphoma patients (OR = 4.349, P = 0.027) however this favoritism was to a lesser extent after mobilization with GCSF and plerixafor." (PMID 38994380, 2022).
lymphoma (continued). "This current study with a longer term follow‐up supports our practice change to collect A‐ALC ≥ 0.5 × 109 cells/kg in addition to CD34 to improve clinical outcomes for lymphoma patients undergoing APBHSCT." (PMID 35846064, 2022). "The numbers of CD34+ cells collected in patients with hematological malignancies (39 multiple myelomas, 11 lymphomas) were determined during mobilization for an autologous hematopoietic stem cell transplantation." (PMID 34356523, 2021). "Others have shown that lymphoma patients’ poor mobilization of autologous stem cells, defined as the inability to obtain ≥1 × 106 CD34+ cells/kg body weight, resulted in substantially lower PFS and OS compared with good mobilizers." (PMID 31570781, 2020). "Collectively, our results indicate that the sub-population of CD34+ clonotypic B-cells that we isolated is a candidate lymphoma stem cell (LSC)." (PMID 32010428, 2020). "An antagonist, AMD3100, is used for the release of CD34+ hematopoietic stem cells from the bone marrow for autologous transplantation for lymphoma or multiple myeloma patients." (PMID 32766282, 2020). "In this study, we identified a minor cell population within clonal B-cells of lymphoma that expresses CD34 with unique features, including resistance to chemotherapy that distinguishes them from the rest of lymphoma cells." (PMID 32010428, 2020). "In veterinary medicine, CD34 expression can be used to suggest an acute leukemia since it is less commonly expressed in malignancies of more mature cells, such as lymphomas and chronic lymphocytic leukemias." (PMID 27639374, 2016). "Four patients with AIDS-related lymphoma received autologous bone marrow transplants with lentiviral-transduced CD34+ HPCs in an effort to treat both lymphoma and HIV/AIDS." (PMID 26019725, 2015). "In the lymphoma trial a significantly higher proportion of patients (59.3%) achieved optimal CD34+ cell collection (≥5 × 106/kg) in the G-CSF plus plerixafor arm compared to the G-CSF plus placebo arm (19.6%)." (PMID 25197663, 2014). "The proportion of the most primitive HSC (CD34+ CD133+ CD38−) has been reported higher in grafts from patients with lymphomas mobilized with chemotherapy/G-CSF plus plerixafor." (PMID 25197663, 2014). "Increased CD133+CD34+VEGFR-2+ endothelial precursor cells (EPCs) are detectable in the peripheral blood of patients with aggressive lymphomas and decrease in number following complete response to chemotherapy." (PMID 21463120, 2011). "CD34+ cells are highly expressed on lymphoma stem cells in bone marrow (BM)." (PMID 41296384, 2025). "CD34 gene expression has been extensively studied in several types of lymphoma." (PMID 40461625, 2025). "Another study involving 33 lymphoma patients with at least one prior mobilization failure and receiving low dose cytarabine-based (400mg/m2/day×3 days) CM reported a mean CD34+ cell count of 4.69×106 (range: 1.5-6.8×106)/kg, whereas in our study, the PMs group had a mean count of 17.99×106/kg." (PMID 39091501, 2024). "Notably, a single apheresis was sufficient to target an adequate number of CD34+ cells for ASCT in 35(89.7%) patients with r/r lymphoma, with 76.9%(30/39) predicted PM patients achieving optimal collection within two apheresis sessions." (PMID 39091501, 2024). "CD34 is a well-known hematopoietic precursor cell marker that has been clinically used to distinguish between acute lymphoblastic leukemia, chronic lymphocytic leukemia, and the leukemic stage (Stage V) of lymphoma." (PMID 37908841, 2023).